RNY4P13 (RNY4 pseudogene 13)
Gene: Miscellaneous RNA gene on chromosome 17 (30,059,052 to 30,059,147, reverse strand). Ensembl gene ENSG00000207011.
Homologues: Orthologues: chimpanzee Y_RNA (100% identical), rabbit Y_RNA (91% identical), rabbit Y_RNA (90% identical), rabbit Y_RNA (89% identical), guinea pig Y_RNA (85% identical). Paralogues in human: RNY4 (92% identical), RNY4P6 (91% identical), RNY4P10 (89% identical), RNY4P3 (88% identical), RNY4P7 (88% identical), Y_RNA (88% identical), RNY4P17 (86% identical), RNY4P19 (86% identical), RNY4P9 (86% identical), Y_RNA (86% identical), RNY4P14 (85% identical), RNY4P23 (85% identical), and 86 more.